TAAR1 (trace amine associated receptor 1)
Description:
Intracellular G protein-coupled receptor for trace amines, which recognizes endogenous amine-containing metabolites such as beta-phenylethylamine (beta-PEA), 3-iodothyronamine (T1AM), isoamylamine (IAA), cadaverine (CAD), cyclohexylamine (CHA), p-tyramine (p-TYR), trimethylamine (TMA), octopamine and tryptamine. Also functions as a receptor for various drugs and psychoactive substances, such as amphetamine and methamphetamine. Unresponsive to classical biogenic amines, such as epinephrine and histamine and only partially activated by dopamine and serotonin. Expressed in both the central and peripheral nervous system: TAAR1 activation regulates the activity of several neurotransmitter signaling pathways by (1) decreasing the basal firing rates of the neurons involved and by (2) lowering the sensitivity of receptors to neurotransmitters. Ligand binding causes a conformation change that triggers signaling via guanine nucleotide-binding proteins (G proteins) and modulates the activity of downstream effectors. TAAR1 is coupled with different G(i)/G(o)-, G(s)- or G(q)/G(11) classes of G alpha proteins depending on the ligand. CAD-binding is coupled to G(i)/G(o) G alpha proteins and mediates inhibition of adenylate cyclase activity. T1AM- or beta-PEA-binding is coupled to G(s) G alpha proteins and mediates activation of adenylate cyclase activity. CHA- or IAA-binding is coupled to G(q)/G(11) G alpha proteins and activates phospholipase C-beta, releasing diacylglycerol (DAG) and inositol 1,4,5-trisphosphate (IP3) second messengers. TMA-binding is coupled with all three G(i)/G(o)-, G(s)- or G(q)/G(11) G alpha protein subtypes. Amphetamine-binding is coupled with G(s)- or G(12)/G(13) G alpha protein subtypes.
Synonyms: TA1; TAR1; TRAR1
Tractability: Small molecule: a drug acting on it is in phase 2 or 3 trials; a structure with a bound ligand is known; a high-quality ligand is known; it belongs to a druggable protein family. Antibody: UniProt places it where antibodies can reach, with high confidence; its Gene Ontology location is reachable by antibodies, with high confidence; UniProt predicts a signal peptide or a membrane-spanning region. PROTAC: a small molecule that binds it is known.
Target class: Monoamine receptor; Trace amine receptor; Membrane receptor; Family A G protein-coupled receptor; Small molecule receptor (family A GPCR)
Chemical probes: PHENETHYLAMINE
Gene: Protein-coding gene on chromosome 6 (132,643,312 to 132,659,182, reverse strand). Ensembl gene ENSG00000146399.
Subcellular location: Endomembrane system; Endoplasmic reticulum membrane; Cell membrane
Pathways (Reactome):
Signal Transduction: Amine ligand-binding receptors; G alpha (s) signalling events
Gene Ontology:
Molecular function: G protein-coupled receptor activity; protein binding; trace-amine receptor activity; G protein-coupled amine receptor activity
Biological process: adenylate cyclase-activating G protein-coupled receptor signaling pathway; adenylate cyclase-inhibiting G protein-coupled receptor signaling pathway; G protein-coupled receptor signaling pathway; phospholipase C-activating G protein-coupled receptor signaling pathway
Cellular component: endomembrane system; plasma membrane; endoplasmic reticulum membrane; membrane
Genetic constraint (gnomAD): Loss-of-function variants: 11 observed, 6.72 expected, observed/expected ratio (o/e) 1.64, 90% interval 0.97 to 1.95. That is too few expected variants to judge how well the gene tolerates losing a copy. Missense variants: 445 observed, 427.45 expected, observed/expected ratio (o/e) 1.04, 90% interval 0.96 to 1.13. Synonymous variants: 153 observed, 139.06 expected, observed/expected ratio (o/e) 1.1, 90% interval 0.96 to 1.26.
Homologues: Orthologues: chimpanzee TAAR1 (99% identical), macaque TAAR1 (96% identical), rabbit TAAR1 (83% identical), rat Taar1 (77% identical), mouse Taar1 (74% identical), guinea pig TAAR1 (74% identical), tropical clawed frog taar1 (63% identical), zebrafish taar1b (47% identical). Paralogues in human: TAAR2 (46% identical), TAAR9 (42% identical), TAAR6 (40% identical), TAAR8 (40% identical), TAAR5 (38% identical), HTR4 (32% identical), DRD1 (31% identical), DRD5 (30% identical), HRH2 (29% identical), HTR1D (29% identical), DRD4 (27% identical), HTR1A (26% identical), and 13 more.
Diseases named in the same sentence as TAAR1 in open-access papers:
TAAR1 is named in the same sentence as 119 diseases in open-access papers, as found by Europe PMC text mining. Sharing a sentence is not in itself a finding about the gene and the disease. The quoted sentences say what the papers report.
schizophrenia (87 papers, 2010 to 2026). A major psychotic disorder characterized by abnormalities in the perception or expression of reality. "In this respect, the trace amine-associated receptor 1 (TAAR1) agonist ulotaront that is effective in schizophrenia was shown to modulate striatal and hippocampal glutamate function in a state-dependent manner." (PMID 38629703, 2024). "Trace amine-associated receptor 1 (TAAR1) is a novel, pharmacological target in the treatment of schizophrenia and other neuropsychiatric conditions." (PMID 39553890, 2024). "TAAR1, in particular, has been implicated as a key regulator of monoaminergic and glutamatergic signaling in brain regions relevant to schizophrenia, as demonstrated in knockout and overexpression models in rodents." (PMID 38798960, 2024). "The trace amine-associated receptor 1 (TAAR1) has recently emerged as a promising therapeutic target for the treatment of schizophrenia and other neuropsychiatric disorders." (PMID 38110609, 2024). "Ulotaront (33, SEP-363856) is a phase-3 clinical lead for the treatment of schizophrenia, displaying TAAR1 (trace-amine-associated receptor 1) and 5-HT1A agonism as mode of action, lacking dopamine D2 and 5-HT2A antagonism." (PMID 39109294, 2024). "Supported by preclinical and recent clinical data, trace amine-associated receptor 1 (TAAR1) agonism has emerged as a potential new treatment approach for schizophrenia." (PMID 38110609, 2024). "TAAR1 single nucleotide variants (SNV) have been found in patients with schizophrenia and metabolic disorders." (PMID 38863077, 2024). "Recent preclinical and clinical evidence suggest that agonists at trace amine-associated receptor 1 (TAAR1) have potential as a new treatment option for schizophrenia." (PMID 38237896, 2024). "The trace amine-associated receptor 1 (TAAR1) plays a significant role as a therapeutic target for schizophrenia, depression, diabetes, and obesity." (PMID 36976665, 2023). "Ulotaront is a trace amine-associated receptor 1 (TAAR1) agonist with additional agonism at 5-HT1A receptors currently in Phase III clinical development for the treatment of schizophrenia." (PMID 37165101, 2023). "The chromosome where TAAR1 is located has been consistently identified by linkage analyses as a susceptibility locus for schizophrenia and bipolar disorder, indicating the potential role of TAAR1 in the progress of depression." (PMID 37002793, 2023). "Trace amine-associated receptor 1 is emerging as a new therapeutic target for schizophrenia and several other neuropsychiatric disorders." (PMID 37509616, 2023). "Ulotaront is a trace amine-associated receptor 1 (TAAR1) agonist in Phase 3 clinical development for the treatment of schizophrenia." (PMID 37165101, 2023). "In particular, the trace amine-associated receptor 1 (TAAR1) has come under the spotlight in recent years as a potential target for new drugs against schizophrenia." (PMID 37184096, 2023). "As preclinical and clinical research progresses, trace amine-associated receptor 1 (TAAR1) is becoming a potential new target for the treatment of schizophrenia." (PMID 37153799, 2023). "TAAR1 is expressed in brain areas that are linked to the emergence of schizophrenia symptoms, e.g., the limbic structures, the frontal cortex and dorsal raphe nucleus." (PMID 36232878, 2022). "Recently, a new promising molecular target for the treatment of schizophrenia—trace amine-associated receptor 1 (TAAR1)—has been identified." (PMID 36359001, 2022). "Several lines of preclinical studies indicate that activation of TAAR1 can indirectly modulate the activity of dopamine, serotonin and glutamate, whose dysregulations are associated with schizophrenia symptoms." (PMID 36232878, 2022). "TAAR1-mediated modulation of cortical glutamatergic transmission has been of particular interest as its deficiency is implicated in the pathophysiology of schizophrenia." (PMID 34947997, 2021).
schizophrenia (continued). "A recent study identified a rare missense variant in TAAR1 (C182F) in three affected members of a small schizophrenia family, and six more variants in sporadic schizophrenia cases." (PMID 31572197, 2019). "Disease states associated with impaired TAAR-1 function include drug abuse, obesity, diabetes, schizophrenia, and PD38–40." (PMID 29367643, 2018). "TAAR1 has been implicated in human conditions including obesity, schizophrenia, depression, fibromyalgia, migraine, and addiction." (PMID 27031617, 2016). "That dogs and their brethren can well tolerate the loss of TAAR1 despite its evolutionary conservation must provoke questions as to the relevance of the gene to schizophrenia or other mental health diseases." (PMID 20167089, 2010). "TAAR1-mediated modulation of cortical glutamatergic transmission has also been of particular interest as its deficiency has been increasingly documented in a range of neuropsychiatric disorders including schizophrenia." (PMID 38110609, 2024). "The aim of the current review article is to present an overview of the preclinical and clinical data to date for ulotaront, a novel trace amine-associated receptor 1 (TAAR1) agonist in development for the treatment of schizophrenia, with potential to be one of the first drugs with a non-D2 MOA." (PMID 37165101, 2023). "In addition, there are encouraging data showing the beneficial effects of using trace amine-associated receptor 1 (TAAR1) agonists to treat the symptoms of schizophrenia." (PMID 36909280, 2023). "TAAR1 is widely expressed throughout the brain and has been found in areas that are associated with the emergence of schizophrenia symptoms, including the frontal cortex as well as the ventral tegmental area and dorsal raphe nucleus, which produce dopamine and serotonin, respectively." (PMID 36359001, 2022). "We provide an overview of TAAR1′s role in regulating monoaminergic and glutamatergic circuits implicated in schizophrenia pathophysiology, and discuss the potential for TAAR1 agonists in psychosis, negative symptomatology, cognition, mood, and anxiety as they relate to schizophrenia." (PMID 34947997, 2021). "Recently, a screen for TAAR1 variants in patients suffering from schizophrenia was performed." (PMID 29225575, 2017). "The present data therefore suggest that TAAR1 may contribute an etiological role to the pathogenesis of schizophrenia, amongst a multiplicity of genetic and environmental risk factors." (PMID 29375386, 2017). "Abnormal levels of TAs has been associated with various neuropathological disorders, including schizophrenia, major depression and Parkinson’s disease; in addition, the TAAR1 gene maps to locus 6q23 have been frequently associated with schizophrenia and bipolar disorder." (PMID 27886063, 2016). "Activation of TAAR1 inhibits midbrain dopaminergic and serotoninergic activity and enhances prefrontal glutamatergic neuron function, which has been associated with a variety of psychiatric disorders, including drug addiction, schizophrenia, and attention‐deficit hyperactivity disorder." (PMID 38317588, 2024). "Thus, it might be important to explore whether TAAR1-dependent neuromodulation caused by 3-MT contributes to pathological manifestations of schizophrenia." (PMID 20976142, 2010). "Selutaront, a novel highly selective TAAR1 agonist with favorable drug-like properties, represents a promising candidate for schizophrenia treatment and provides mechanistic insights into TAAR1-targeted therapy." (PMID 41808867, 2026). "Among these, TAAR1 has received particular attention due to its established role in the neurobiology of major psychiatric and behavioral disorders, including schizophrenia, addiction, mood disorders, and stress-related conditions." (PMID 41462983, 2025). "TAAR1 has emerged as a promising therapeutic target, with agonists currently in clinical trials for schizophrenia." (PMID 40564112, 2025).
schizophrenia (continued). "The discovery of TAAR1-mediated modulation of dopaminergic neurotransmission led to the investigation of TAAR1 agonists as potential therapeutics for various psychiatric disorders including schizophrenia and substance use disorders." (PMID 40840012, 2025). "Ulotaront is an agent that acts as a ”trace amine-associated receptor 1” (TAAR1) agonist with 5-HT1A agonist activity, showing promising but preliminary results in the treatment of schizophrenia, free of extrapyramidal symptoms or metabolic side effects." (PMID 40430486, 2025). "Today, TAAR1 is being actively studied in the context of mental and neuropsychiatric diseases, and TAAR1 agonists are being considered therapeutic agents for schizophrenia, anxiety, and depression treatment." (PMID 40564112, 2025). "Ulotaront (SEP-363856), a TAAR1 agonist, has demonstrated efficacy in treating schizophrenia symptoms in clinical trials." (PMID 41373485, 2025). "TAAR1 agonists such as ulotaront represent a novel and increasingly compelling pharmacological class, originally developed for schizophrenia but now drawing broader interest due to their modulatory effects on monoaminergic and stress-responsive systems." (PMID 41462983, 2025). "TAAR1 is the best-investigated receptor of this family, and TAAR1 agonists are already being tested in clinical studies for the treatment of schizophrenia, anxiety, and depression." (PMID 40564112, 2025). "While more research is needed, TAAR1 agonists represent a promising new class of drugs for treating various psychiatric disorders, including schizophrenia, depression, and anxiety." (PMID 41373485, 2025). "Clinical trials have shown that ulotaront (SEP-363856), a novel TAAR1 agonist, produces significant efficacy in schizophrenia and major depressive disorder." (PMID 41462983, 2025). "Recent research has focused on trace amine-associated receptor 1 (TAAR1) as a promising target for treating psychiatric disorders, particularly schizophrenia." (PMID 41373485, 2025). "The current data further supports evaluation of TAAR1 agonists for the treatment of metabolic disorders including metabolic dysregulation in patients with schizophrenia." (PMID 38237896, 2024). "In particular, TAAR1 agonists have generated significant interest as potential treatments for schizophrenia due to their robust antipsychotic-like effects in rodent models and prominent regulation of dopaminergic tone." (PMID 38110609, 2024). "In particular, we highlight the trend of using cryo-EM structures and delineating novel signalling mechanisms to develop TAAR1 agonists with optimised pharmacological profiles to treat schizophrenia-like phenotypes." (PMID 39553890, 2024). "Initially, TAAR1-KO rodents were proposed as models of schizophrenia, showing not only enhanced responses to amphetamine and deficits in sensorimotor gating but also altered sleep-wake cycles and increased impulsivity." (PMID 39748904, 2024). "TAAR1 is a novel target for several neurological disorders,including schizophrenia, depression, and substance abuse." (PMID 39358311, 2024). "TAAR1 agonists, including the Phase 3 clinical development candidate ulotaront, have recently emerged as a potential new treatment approach in schizophrenia and other psychiatric disorders including depression, anxiety and substance abuse." (PMID 38237896, 2024). "TAAR1 is emerging as a potential new therapeutic target for schizophrenia and several other neuropsychiatric disorders." (PMID 38110609, 2024). "•TAAR1 agonists, including schizophrenia drug candidate ulotaront, exhibit weight-lowering and glucoregulatory effects in rodents." (PMID 38237896, 2024). "The impact of TAAR1 on glutamate-dopamine circuits across multiple disease-relevant brain regions speaks to the potential of this target not only for schizophrenia but also for CNS disorders in general." (PMID 38110609, 2024).